SEPTIN10 (septin 10)
Description:
Filament-forming cytoskeletal GTPase. May play a role in cytokinesis (Potential).
Synonyms: SEPT10; FLJ11619; Septin-10
Tractability: PROTAC: ubiquitination databases record sites on it.
Gene: Protein-coding gene on chromosome 2 (109,542,797 to 109,614,157, reverse strand). Ensembl gene ENSG00000186522.
Subcellular location: Cytoplasm; Cytoplasm, cytoskeleton; Cell projection, cilium, flagellum
Subcellular location (Human Protein Atlas): Actin filaments; Annulus; Microtubules
Gene Ontology:
Molecular function: protein binding; GTPase activity; molecular adaptor activity; GTP binding
Biological process: cytoskeleton-dependent cytokinesis; intracellular protein localization
Cellular component: actin cytoskeleton; microtubule cytoskeleton; sperm annulus; cell division site; septin complex; septin ring; cytoplasm; cytoskeleton; motile cilium
Genetic constraint (gnomAD): Loss-of-function variants: 47 observed, 41.81 expected, observed/expected ratio (o/e) 1.12, 90% interval 0.89 to 1.43. The upper end of that interval is the gene's LOEUF score, 1.43, which puts it in group 5 of 6, group 1 being the genes least tolerant of losing a copy. Missense variants: 559 observed, 475.65 expected, observed/expected ratio (o/e) 1.18, 90% interval 1.1 to 1.26. Synonymous variants: 146 observed, 153.85 expected, observed/expected ratio (o/e) 0.95, 90% interval 0.83 to 1.09.
Homologues: Orthologues: pig SEPTIN10 (88% identical), macaque SEPTIN10 (85% identical), guinea pig SEPTIN10 (84% identical), rat Septin10 (81% identical), mouse Septin10 (80% identical), rabbit SEPTIN10 (79% identical), zebrafish septin10 (73% identical), tropical clawed frog septin10 (71% identical), Drosophila melanogaster Septin5 (56% identical). Paralogues in human: SEPTIN11 (69% identical), SEPTIN8 (69% identical), SEPTIN14 (68% identical), SEPTIN6 (67% identical), SEPTIN7 (39% identical), SEPTIN5 (31% identical), SEPTIN2 (31% identical), SEPTIN3 (30% identical), SEPTIN9 (30% identical), SEPTIN1 (30% identical), SEPTIN12 (26% identical), TMEM250 (5% identical).
Diseases named in the same sentence as SEPTIN10 in open-access papers:
SEPTIN10 is named in the same sentence as 7 diseases in open-access papers, as found by Europe PMC text mining. Sharing a sentence is not in itself a finding about the gene and the disease. The quoted sentences say what the papers report.
Cirrhosis (1 paper, 2016). A chronic disorder of the liver in which liver tissue becomes scarred and is partially replaced by regenerative nodules and fibrotic tissue resulting in loss of liver function. "Random Forest analysis predicted that most septins are affected in HCV-induced cirrhosis when compared to normal liver, while septin 10 was less affected." (PMID 27417143, 2016).
colon cancer (1 paper, 2023). "Accordingly, both technologies reported the overexpression of STIM1, MBP, SEPTIN9, and SEPTIN10 and the downregulation of CRACR2A, ORMDL3, SARAF, SEPTIN3, and SEPTIN6 in colon cancer cells." (PMID 36900391, 2023).
dermatitis (1 paper, 2024). An inflammatory process affecting the skin. "We identified two additional gene-trait association at nominal significance (p < 0.05): CH variants in FLG that are associated with an increased risk of dermatitis (p = 0.0092), and CH variants in SEPTIN10 that are associated with hyperplasia of prostate (p = 0.011)." (PMID 38944039, 2024).
cancer (5 papers, 2016 to 2022). A tumor composed of atypical neoplastic, often pleomorphic cells that invade other tissues. "SEPTIN10 is associated with B cell leukemias, while TRIP10 is involved in tumorigenesis and cancer progression." (PMID 36139690, 2022). "Aberrant expression of septins is involved in tumorigenesis, e.g., overexpression of septin-2,-8,-9,-11 and downregulation of septin-4 and septin-10 have been identified in a wide variety of cancer types." (PMID 27525972, 2016).
SEPTIN10 also shares sentences with these, for which no sentence is quoted: tumor (2 papers); breast carcinoma (1); hyperplasia of prostate (1).